GCNT2 (glucosaminyl (N-acetyl) transferase 2 (I blood group))
Description:
Branching enzyme that converts linear into branched poly-N-acetyllactosaminoglycans. Introduces the blood group I antigen during embryonic development. It is closely associated with the development and maturation of erythroid cells. [Isoform C]: Determines the expression of the blood group I antigen in erythrocytes.
Synonyms: GCNT5; IGNT; II; NACGT1; NAGCT1; bA421M1.1; bA360O19.2; ULG3; CCAT; CTRCT13; GCNT2C
Tractability: Antibody: UniProt predicts a signal peptide or a membrane-spanning region. PROTAC: ubiquitination databases record sites on it.
Gene: Protein-coding gene on chromosome 6 (10,492,223 to 10,629,368, forward strand). Ensembl gene ENSG00000111846.
Subcellular location: Golgi apparatus membrane
Subcellular location (Human Protein Atlas): Golgi apparatus
Gene Ontology:
Molecular function: N-acetyllactosaminide beta-1,6-N-acetylglucosaminyltransferase activity; protein binding; acetylglucosaminyltransferase activity; glycosyltransferase activity; UDP-glycosyltransferase activity
Biological process: glycoprotein biosynthetic process; maintenance of lens transparency; negative regulation of cell-substrate adhesion; positive regulation of cell migration; positive regulation of epithelial to mesenchymal transition; positive regulation of ERK1 and ERK2 cascade; positive regulation of heterotypic cell-cell adhesion; positive regulation of phosphatidylinositol 3-kinase/protein kinase B signal transduction; post-transcriptional regulation of gene expression; transforming growth factor beta receptor signaling pathway; glycosaminoglycan biosynthetic process; multicellular organism development; positive regulation of cell population proliferation
Cellular component: membrane; Golgi membrane
Genetic constraint (gnomAD): Loss-of-function variants: 27 observed, 27.2 expected, observed/expected ratio (o/e) 0.99, 90% interval 0.73 to 1.37. The upper end of that interval is the gene's LOEUF score, 1.37, which puts it in group 5 of 6, group 1 being the genes least tolerant of losing a copy. Missense variants: 527 observed, 452.58 expected, observed/expected ratio (o/e) 1.16, 90% interval 1.08 to 1.25. Synonymous variants: 200 observed, 183.28 expected, observed/expected ratio (o/e) 1.09, 90% interval 0.97 to 1.23.
Homologues: Orthologues: chimpanzee GCNT2 (99% identical), macaque GCNT2 (72% identical), dog GCNT2 (69% identical), guinea pig GCNT2 (68% identical), pig GCNT2 (66% identical), rat Gcnt2 (66% identical), tropical clawed frog pak1ip1 (59% identical), Caenorhabditis elegans gly-16 (24% identical), Caenorhabditis elegans gly-18 (24% identical), Caenorhabditis elegans gly-17 (24% identical), Caenorhabditis elegans gly-19 (24% identical), Caenorhabditis elegans gly-15 (22% identical), and 14 more. Paralogues in human: GCNT7 (39% identical), GCNT4 (38% identical), GCNT3 (38% identical), GCNT1 (37% identical), XYLT2 (21% identical), XYLT1 (19% identical), WSCD2 (10% identical), WSCD1 (10% identical).
Diseases named in the same sentence as GCNT2 in open-access papers:
GCNT2 is named in the same sentence as 41 diseases in open-access papers, as found by Europe PMC text mining. Sharing a sentence is not in itself a finding about the gene and the disease. The quoted sentences say what the papers report.
breast carcinoma (13 papers, 2012 to 2025). "In breast cancer, GCNT2 is also associated with invasiveness by regulating epithelial-to-mesenchymal transition." (PMID 40149658, 2025). "In highly metastatic breast cancer lines and tumors, GCNT2 is overexpressed, an occurrence associated with enhanced cell detachment, adhesion to endothelial cells, migration and invasion in vitro, and lung metastasis in vivo." (PMID 24753248, 2014). "Forexample, GCNT2, which is a gene-encoding glucosaminyl (N-acetyl) transferase 2, contributesto breast cancer metastasis with preferential expression in basal-like breast cancer." (PMID 22992780, 2012). "In fact, the oncogenic function of GCNT2 was reported in the most investigated cancers, including breast cancer, prostate cancer, and esophageal carcinoma." (PMID 40034691, 2025). "Specifically, GCNT2 is overexpressed in highly metastatic breast cancer cell lines of human and mouse origin and breast tumor samples." (PMID 37870443, 2023). "Previous functional studies showed that ectopic expression of GCNT2 enhanced cell migration and invasion in vitro, and lung metastasis of breast cancer cells in vivo." (PMID 35780128, 2022). "GCNT2 is overexpressed in highly metastatic breast cancer, and its expression correlates with adverse pathological features and progression of disease." (PMID 32301282, 2020). "GCNT2, recently found to be overexpressed in highly metastatic breast cancer cell lines and basal-like breast cancer, interacts with TGF-β to promote epithelial-to-mesenchymal transition, enhancing the metastatic potential of breast cancer." (PMID 23544012, 2013). "The expression of GCNT2 is high in breast cancer and regulates cancer cell invasion and migration." (PMID 34069424, 2021). "Elevation of FUT1, GCNT2, and GCNT3 expression as seen in RWPE1 cells cultured under hypoxia may similarly underlie colon and breast cancer survival responses to hypoxia and promote invasion and metastasis." (PMID 24753248, 2014). "Downregulation of GCNT2 expression prevented the TGF-β-induced EMT process, as well as migration and invasion of breast cancer cells." (PMID 34069424, 2021). "Recently, GCNT2 has been reported to be involved in metastasis of breast cancer through TGF-β signaling, and blocking the expression of GCNT2 was shown to abrogate the tumor cell migration and invasion." (PMID 24753245, 2014).
melanoma (11 papers, 2018 to 2025). A malignant, usually aggressive tumor composed of atypical, neoplastic melanocytes. "We found that GCNT2 expression in both human and murine melanomas is inversely associated with metastatic potential." (PMID 40430022, 2025). "Extensive research on melanoma has illustrated the opposite role of GCNT2 in the pathogenesis of the disease, with loss of GCNT2/I-antigen contributing to metastasis and progress." (PMID 40034691, 2025). "GCNT2 has been widely studied in melanoma, the loss of which brings corresponding loss of I-antigen and thus enhances melanoma growth and metastasis." (PMID 36611197, 2023). "A recent study revealed that loss of GCNT2/I-branched glycans in melanomas regulates multiple cell surface glycoprotein signaling pathways and promotes melanoma growth and survival." (PMID 34440905, 2021). "Loss of GCNT2/I-branches increased melanoma xenograft growth and enhanced three-dimensional colony formation and survival." (PMID 30135430, 2018). "Functionally, loss of GCNT2/I-branched glycans promoted melanoma xenograft growth, colony formation, and cell survival, while overexpression of GCNT2/I-branched glycans negatively regulated melanoma xenograft growth, colony formation, and cell survival." (PMID 30135430, 2018). "Treatment of GCNT2 KD, GCNT2 OE and control melanoma cell variants with IGF-1, the cognate ligand for IGF1R, revealed that low GCNT2/I-branched glycan levels increased melanoma cell proliferation." (PMID 30135430, 2018). "Together, these data indicate that loss of GCNT2/I-branched glycans enhances melanoma growth and survival." (PMID 30135430, 2018). "Here, we report that, compared to NHEMs, melanomas downregulate the glycosyltransferase, GCNT2, and display a corresponding loss of I-branched glycans on the cell surface." (PMID 30135430, 2018). "We found that GCNT2 inversely correlated with clinical progression and that loss of GCNT2 increased melanoma xenograft growth, promoted colony formation, and enhanced cell survival." (PMID 30135430, 2018). "This gene signature revealed that, compared to normal melanocytes, melanomas downregulate I-branching glycosyltransferase, GCNT2, leading to a loss of cell-surface I-branched glycans." (PMID 30135430, 2018). "Of note, cell-surface expression of integrin β3 in one of the two GCNT2 KD melanoma cell variants, as well as cell-surface expression of integrin αV in both GCNT2 KD melanoma cell variants was significantly decreased compared to control cells." (PMID 30135430, 2018). "Overall, our study reveals that loss of GCNT2/I-branched glycans in melanomas regulates multiple cell surface glycoprotein signaling pathways and promotes melanoma growth and survival." (PMID 30135430, 2018). "Functionally, KD of GCNT2 and loss of I-branched glycans increased melanoma tumor xenograft growth and tumor mass compared to control cells." (PMID 30135430, 2018). "In our model, we believe that the downregulation of GCNT2 is important for the loss of I-branched glycans in melanoma cells and perhaps even for the increase in extended i-linear polyLacNAcs through less donor sugar competition between B3GNT and GCNT2." (PMID 30135430, 2018). "In melanoma cells, loss of GCNT2 leads to melanoma progression, tumor cell growth, and survival." (PMID 40149658, 2025). "Here the authors provide data that show melanoma cells downregulate GCNT2 with consequent loss of I-branched glycans; this leads to the formation of extended i-linear glycans and enhances melanoma growth via increases, in part, by IGF-1- and extracellular matrix-induced signaling." (PMID 30135430, 2018). "Since glycosyltransferases are global regulators of protein glycosylation, we hypothesized that loss of GCNT2 and its effects on melanoma growth and survival likely arises through modification of numerous glycoprotein targets." (PMID 30135430, 2018).
melanoma (continued). "Currently, a multitude of studies are focused on identifying the most virulent, stem-like cancer cells and their progeny within tumors, and perhaps loss of GCNT2 and a corresponding increase in the presence of i-linear glycans is an indication of a dedifferentiated melanoma cell." (PMID 30135430, 2018). "Analysis of The Cancer Genome Atlas (TCGA) data revealed that GCNT2 levels are significantly higher in primary melanoma samples (n = 103) than in metastatic cases (n = 368) (p < 0.05)." (PMID 40430022, 2025). "Using melanoma cells with enforced GCNT2 expression, data demonstrated that high GCNT2 levels impede Gal-3 binding to its surface receptors, with the glycoprotein receptor β1 integrin serving as a representative ligand model." (PMID 40430022, 2025). "Our goal was to elucidate how GCNT2 expression and the resulting glycosylation patterns impact Gal-3 binding and the subsequent signaling pathways that contribute to melanoma progression." (PMID 40430022, 2025). "The unique expression of GCNT2 in melanoma has been explored for the prediction of survival and the therapeutic target." (PMID 40034691, 2025). "Collectively, our findings provide critical insights into the glycosylation-dependent mechanisms regulating melanoma progression and highlight the protective role of GCNT2/I-branching in mitigating Gal-3-mediated aggressive disease." (PMID 40430022, 2025). "This study provides compelling evidence for the role of GCNT2-mediated I-branching glycosylation in modulating Gal-3 interactions and subsequent cellular behaviors in melanoma." (PMID 40430022, 2025). "Here, we report that GCNT2/I-branching significantly impairs Gal-3 binding to melanoma cell receptors, particularly β1 integrin, and diminishes Gal-3-induced ERK phosphorylation, BCL2 expression, cell proliferation, and migration." (PMID 40430022, 2025). "They found that melanomas exhibit significant transcriptional changes in glycosylation-related genes, and GCNT2 is one of these signatures." (PMID 40149658, 2025). "In melanoma, GCNT2 inhibits tumor proliferation, in contrast to the effect observed in other cancers, where it is involved in tumor invasion." (PMID 36143291, 2022). "According to recent research, I-antigen-forming β1,6 N-acetylglucosaminyltransferase 2 (GCNT2) was proposed as a potential novel biomarker for melanoma progression." (PMID 36143291, 2022). "Recently, Sweeney and colleagues demonstrated that melanomas downregulate the glycosyltransferase beta-1,6-N-acetylglucosaminyltransferase (GCNT2) promoting melanoma xenograft growth, colony formation, and cell survival." (PMID 30891426, 2019). "Compared with normal human epidermal melanocytes (NHEMs), this glycome gene blueprint revealed that the β1,6-N-acetylglucosaminyltransferase, GCNT2, is downregulated in melanomas." (PMID 30135430, 2018). "While we did not observe a significant decrease in Gal-1-binding, we did observe a significant decrease in both exogenous and endogenous Gal-3-binding to GCNT2/I-branched glycan expressing melanoma cells." (PMID 30135430, 2018). "Staining a panel of clinical specimens, including normal skin, benign nevi, and primary and metastatic melanomas, revealed that GCNT2 is downregulated as melanomas progress from a normal to a malignant and metastatic state." (PMID 30135430, 2018). "Conversely, overexpression of GCNT2/I-branched glycans decreased melanoma tumor xenograft growth and tumor mass compared to control cells." (PMID 30135430, 2018). "A key finding in our studies is that melanomas significantly downregulate GCNT2 and I-branched glycans compared to NHEMs." (PMID 30135430, 2018). "Together, these data further support the role of GCNT2/I-branched glycans in regulating melanoma cell growth and survival." (PMID 30135430, 2018).
melanoma (continued). "Taken together, these data indicate that GCNT2 expression is inversely correlated with melanoma progression and highlights its potential use as a biomarker that correlates with stage of disease and associated virulence." (PMID 30135430, 2018). "Of these, the downregulation of β1,6-N-acetylglucosaminyltransferase, GCNT2, in melanoma cells was of particular interest, as this is the enzyme that catalyzes the transfer of N-acetylglucosamine to galactose residues on polyLacNAcs to form I-branched glycans." (PMID 30135430, 2018). "To dissect how integrin:ECM engagement regulates melanoma cell survival, we plated GCNT2 KD, GCNT2 OE, and control melanoma cells on ECM and analyzed integrin:ECM induced signaling." (PMID 30135430, 2018). "In summary, these findings support a model demonstrating that, throughout malignant progression, melanomas decrease expression of GCNT2/I-branched glycans." (PMID 30135430, 2018). "Of note, although GCNT2 KD melanoma cells plated on plastic did show a slight increase in expression of prosurvival genes BCL-2 and BCL-XL, upon engagement with ECM, GCNT2 KD melanoma cells significantly upregulated the expression of both BCL-2 and BCL-XL." (PMID 30135430, 2018). "While effects associated with these N-glycoprotein targets act as surrogates for global N-glycan modifications, overall they implicate GCNT2/I-branched glycans as a negative regulator of melanoma growth." (PMID 30135430, 2018). "Conversely, overexpression of GCNT2 decreased melanoma xenograft growth, inhibited colony formation, and increased cell death." (PMID 30135430, 2018). "Similarly, the modulation of melanoma cell proliferation and migration by GCNT2/I-branching can be attributed, at least in part, to the altered interactions between Gal-3 and its surface receptors, particularly integrins." (PMID 40430022, 2025). "Our observations align with recent studies showing that the tandem-repeat galectin Gal-8 preferentially binds to melanoma cells with reduced GCNT2/I-branching and elevated levels of i-linear poly-LacNAcs, resulting in enhanced activity of pro-tumorigenic signaling pathways." (PMID 40430022, 2025). "Our data demonstrate that GCNT2 expression is inversely correlated with the metastatic potential of human and murine melanomas, reinforcing our previously reported findings of GCNT2 as a suppressor of melanoma progression." (PMID 40430022, 2025). "Similarly, the interrogation of the RNA sequencing (RNA-seq) dataset GSE122789 showed decreased GCNT2 expression in the highly metastatic B16/BL6 murine melanoma cell line relative to its parental, less metastatic B16 cell line." (PMID 40430022, 2025). "Furthermore, this study clearly showed that knockdown of GCNT2 significantly enhances melanoma xenograft growth and three-dimensional colony formation and survival, whereas GCNT2 overexpression has the opposite effect." (PMID 34440905, 2021). "Loss of the β1,6-GlcNAc-transferase GCNT2 that synthesizes the I antigen branches of N-acetyllactosamine chains was observed in melanomas, and a knockdown of GCNT2 activated the IGFR1-mediated signaling pathways and Tyr phosphorylation upon IGF1 induction in melanoma cells." (PMID 34069424, 2021). "Therefore, to assess why melanomas decrease expression of GCNT2/I-branched glycans, we generated stable GCNT2 knockdown (KD) and GCNT2 overexpressing (OE) human melanoma cell lines." (PMID 30135430, 2018). "In addition, data mining further confirmed lower GCNT2 mRNA levels in clinical metastatic melanoma specimens compared to primary melanoma specimens from two of three independent clinical cohorts." (PMID 30135430, 2018). "Taken together, these results suggest that GCNT2/I-branching may inhibit melanoma survival, in part, by decreasing integrin-mediated cell signaling." (PMID 30135430, 2018). "Next, we analyzed the role of GCNT2/I-branched glycans on melanoma growth and survival." (PMID 30135430, 2018).